DLX2 (distal-less homeobox 2)
Description:
Acts as a transcriptional activator (By similarity). Activates transcription of CGA/alpha-GSU, via binding to the downstream activin regulatory element (DARE) in the gene promoter (By similarity). Plays a role in terminal differentiation of interneurons, such as amacrine and bipolar cells in the developing retina. Likely to play a regulatory role in the development of the ventral forebrain (By similarity). May play a role in craniofacial patterning and morphogenesis (By similarity).
Synonyms: TES-1; TES1
Tractability: PROTAC: ubiquitination databases record sites on it.
Gene: Protein-coding gene on chromosome 2 (172,099,438 to 172,102,900, reverse strand). Ensembl gene ENSG00000115844.
Subcellular location: Nucleus
Subcellular location (Human Protein Atlas): Nuclear speckles
Gene Ontology:
Molecular function: protein binding; sequence-specific double-stranded DNA binding; DNA-binding transcription factor activity; DNA-binding transcription factor activity, RNA polymerase II-specific; RNA polymerase II cis-regulatory region sequence-specific DNA binding; transcription cis-regulatory region binding; chromatin binding; DNA binding; DNA-binding transcription activator activity, RNA polymerase II-specific; RNA polymerase II transcription regulatory region sequence-specific DNA binding; single-stranded RNA binding
Biological process: brain development; cell differentiation; embryonic skeletal system development; negative regulation of photoreceptor cell differentiation; positive regulation of amacrine cell differentiation; positive regulation of cell differentiation; positive regulation of transcription by RNA polymerase II; regulation of transcription by RNA polymerase II; regulation of DNA-templated transcription
Cellular component: chromatin; nucleus
Genetic constraint (gnomAD): Loss-of-function variants: 8 observed, 27.31 expected, observed/expected ratio (o/e) 0.29, 90% interval 0.17 to 0.53. The upper end of that interval is the gene's LOEUF score, 0.53, which puts it in group 2 of 6, group 1 being the genes least tolerant of losing a copy. Missense variants: 421 observed, 438.82 expected, observed/expected ratio (o/e) 0.96, 90% interval 0.88 to 1.04. Synonymous variants: 210 observed, 192.17 expected, observed/expected ratio (o/e) 1.09, 90% interval 0.98 to 1.23.
Homologues: Orthologues: chimpanzee DLX2 (99% identical), guinea pig DLX2 (96% identical), pig DLX2 (95% identical), mouse Dlx2 (95% identical), rat Dlx2 (94% identical), macaque DLX2 (66% identical), tropical clawed frog dlx2 (62% identical), zebrafish dlx2a (58% identical), zebrafish dlx2b (50% identical), Drosophila melanogaster Dll (29% identical), Caenorhabditis elegans ceh-43 (26% identical). Paralogues in human: DLX3 (43% identical), DLX5 (42% identical), DLX6 (31% identical), DLX1 (29% identical), DLX4 (26% identical), BSX (15% identical), NANOG (15% identical), NANOGP8 (15% identical), VENTX (13% identical).
Diseases named in the same sentence as DLX2 in open-access papers:
DLX2 is named in the same sentence as 57 diseases in open-access papers, as found by Europe PMC text mining. Sharing a sentence is not in itself a finding about the gene and the disease. The quoted sentences say what the papers report.
breast carcinoma (8 papers, 2010 to 2024). "ROS activates the Distal-less homeobox-2 (Dlx-2)/Snail axis in breast cancer, causing EMT, glycolytic switch, and mitochondrial suppression, which are essential for metastasis." (PMID 39309448, 2024). "We previously reported the increased expression of DLX2 in human lung and breast cancer cell lines exposed to single IR at 8 Gy and these cells showed TGF-β-mediated EMT by Smad2/3 signaling." (PMID 33924205, 2021). "For example, during glucose deprivation-driven metabolic stress in breast cancer cells, DLX2 was induced by reactive oxygen species, and knockdown of DLX2 protected cells from necrosis." (PMID 34203994, 2021). "Dlx-2 has been shown to be expressed at higher levels in human breast cancers compared to other Dlx genes, including Dlx-1, Dlx-3, Dlx-4, and Dlx-6, although its precise roles in tumor biology are not clear." (PMID 21917150, 2011). "Herein we show that a DLX2-to-DLX5/6 switch in gene expression occurs during metastasis formation by MDA-MB-231 human breast carcinoma cells injected into nude mice." (PMID 21108812, 2010). "Our studies indicate that DLX genes are involved in human breast cancer progression, and that DLX2 and DLX5 genes might serve as prognostic markers." (PMID 21108812, 2010). "In this study, we have investigated the role of DLX2 in association with stem cell-like properties and epithelial to mesenchymal transition (EMT) and its regulation by Smad2/3 signaling in irradiated A549 human lung cancer cells and MDA-MB-231 human breast cancer cells." (PMID 26799321, 2016). "The expression of DLX2 and DLX5 was evaluated in 408 primary human breast cancers examining the GSE1456 and GSE3494 microarray datasets." (PMID 21108812, 2010). "A preliminary analysis on human samples showed inhibition of DLX2 and induction of DLX5 expression in breast cancer, as compared with normal breast tissue." (PMID 21108812, 2010). "To analyze the role of DLX2, DLX5, and DLX6 in breast primary tumor and metastasis formation, we used an experimental model of breast cancer metastasis." (PMID 21108812, 2010). "Moreover, expression of DLX2 and DLX5 have been reported to be mutually exclusive in breast cancer, with DLX2 expression being significantly correlated with a favorable prognosis, whereas DLX5 was associated with metastasis." (PMID 34203994, 2021). "Dlx-2 and Snail expression were higher in breast cancer tissues compared to matched non-tumorigenic tissues." (PMID 26771232, 2016). "In this study, we have investigated the role of DLX2 in expression of CSCs and EMT-related genes, migration and invasion ability, radioresistance in irradiated A549 human lung cancer cells and MDA-MB-231 human breast cancer cells." (PMID 26799321, 2016). "Our data suggest that DLX2 and DLX5 are involved in human breast cancer progression, and that they might serve as good or poor prognostic markers, respectively." (PMID 21108812, 2010). "Furthermore, analysis of microarray data on human breast tumors showed that breast cancer patients with DLX2 expression had on average better prognosis and less incidence of relapse, while DLX5 expression and DLX2 downregulation, was related to a subset of more aggressive tumors." (PMID 21108812, 2010).
autism (6 papers, 2005 to 2025). Persistent deficits in social interaction and communication and interaction as well as a markedly restricted repertoire of activity and interest as well as repetitive patterns of behavior. "One of these, rs2228184, corresponding to our DLX2 SNP-4, a synonymous coding sequence variant, showed marginal association to autism." (PMID 16266434, 2005). "HOX genes (HOXD1) map into human chromosome 2 region (2q31–2q33), where GAD1 and DLX2 also reside, and while linkage to autism is weak for the genes in this region (e.g., GAD1), the sheer proximity could potentially signify transcriptional coregulation." (PMID 39758604, 2025). "A DLX2 direct target Grin2b is linked to schizophrenia, epilepsy, intellectual disability, and autism, which provides evidence that DLX2 may contribute to neural diseases." (PMID 35546872, 2022). "The fact that 4.4% of autistic probands had non-synonymous DLX2 and DLX5 variants (5% when including the DLX5/6 intergenic enhancer variant) could reflect the multifactorial etiology of autism." (PMID 16266434, 2005). "Finally, perhaps the variants in DLX2, DLX5 and ARX, all of which alter the development of forebrain GABAergic neurons, are providing a clue that an increase in the ratio of excitation/inhibition underlies some forms of autism." (PMID 16266434, 2005). "The two lowest scores, 68 and 85, occurred in two sibs (one with autism, the other with "not quite autism") who both were heterozygous for the DLX2 Serine insertion/deletion and both had early trigonocephaly which normalized." (PMID 16266434, 2005). "While the identification of variants that generate non-conserved amino acid changes in DLX2 and DLX5 in autistic people suggests that the DLX genes could contribute to autism susceptibility, there are limitations to our study." (PMID 16266434, 2005).
hepatocellular carcinoma (6 papers, 2020 to 2025). A malignant tumor that arises from hepatocytes. "Overexpressed distal-less homeobox 2 (DLX2) is associated with adverse clinical outcomes in hepatocellular carcinoma and gastric adenocarcinoma." (PMID 36106335, 2022). "Preclinical studies in hepatocellular carcinoma have demonstrated that DLX2 silencing suppresses tumor proliferation and metastasis." (PMID 41244921, 2025). "AcRoots also suppressed DLX2/TARBP2/JNK/AKT pathway to inhibit hepatocellular carcinoma cell proliferation and metastasis." (PMID 35152841, 2022). "The overexpression of DLX2 was related to poor prognosis of hepatocellular carcinoma, glioblastoma, etc." (PMID 36317140, 2022).
prostate carcinoma (5 papers, 2014 to 2021). A carcinoma that arises from epithelial cells of the prostate gland. "By inspection, we also identified at least 10 additional transcription factors within 500 kb of 9 other GWAS loci, that are also reasonable candidates for contributing to prostate cancer risk: SOX13, ZFP36L2, ATOH8, DLX1 & DLX2 (same locus), GATA2, SKIL, SP8, ASCL2, and DPF1." (PMID 24497837, 2014). "Interestingly, Abnormal expression of DLX2 was found in malignant progression of human solid tumors including gastric adenocarcinoma, acute lymphoblastic leukemia, melanoma, glioma, breast, lung and prostate cancer." (PMID 26799321, 2016). "In the colon cfDNA pool, TFs EVX2, DLX2, HNF1A, HNF4A, and HNF4G and TFs AR and HOXB13 in the prostate cancer cfDNA pool had increased accessibilities, whereas FOXA1 exceeded the >5 z-score threshold in both the prostate and breast pool." (PMID 31604930, 2019).
colorectal cancer (3 papers, 2021 to 2025). A primary or metastatic malignant neoplasm that affects the colon or rectum. "DLX2 has also emerged as a poor prognostic factor in colorectal cancer and liver cancer, where it promotes sorafenib resistance via EMT activation and ERK signaling." (PMID 41244921, 2025). "DLX2 and PCOLCE2 are potential tumor markers of early-onset colorectal cancer." (PMID 34789836, 2021). "The high expression of DLX2 and PCOLCE2 may influence and participate in the occurrence of colorectal cancer, and lead to the occurrence of early-onset colorectal cancer." (PMID 34789836, 2021). "DLX2 was demonstrated to be associated with EMT in osteosarcoma in previous studies and its increased expression was associated with advanced gastric adenocarcinoma, but no article defining the relationship between DLX2 and poor prognosis in colorectal cancer could be found yet." (PMID 39717768, 2024).
glioma (3 papers, 2016 to 2022). A benign or malignant brain and spinal cord tumor that arises from glial cells (astrocytes, oligodendrocytes, ependymal cells). "Our research group has also shown that distal-less homeobox 2 (DLX2), an essential transcription factor induced by BMPs, is important for neural differentiation and apoptosis of glioma-initiating cells." (PMID 35693928, 2022). "Among them, DLX2 plays a crucial role in the development of many human cancers, including glioma and gastric adenocarcinoma cancers." (PMID 31920462, 2020).
Huntington disease (3 papers, 2020 to 2021). Huntington disease (HD) is a rare neurodegenerative disorder of the central nervous system characterized by unwanted choreatic movements, behavioral and psychiatric disturbances and dementia. "In Huntington’s disease model mice, combinatorial expression of NeuroD1 and Dlx2 in striatal astrocytes induces conversion into GABAergic neurons." (PMID 34068607, 2021). "In a separate study on Huntington's disease, we have discovered that combining NeuroD1 and Dlx2 together can successfully convert striatal astrocytes into GABAergic neurons." (PMID 33425896, 2020). "More recently, by combining NeuroD1 and Dlx2 together, we have demonstrated that astrocytes in the striatum of R6/2 mouse model for Huntington's disease can be converted into GABAergic neurons." (PMID 33425896, 2020). "By combining NeuroD1 and Dlx2 together, we further demonstrated that astrocytes in the striatum of mouse model with Huntington’s disease can be directly converted in medium spinal neurons, which not only improved motor functions but also extended the life span of HD mice." (PMID 33224952, 2020).
lung carcinoma (3 papers, 2016 to 2021). "During this study, we showed that repeated IR induced cancer stemness properties and EMT with the upregulation of TGF-β and DLX2 signaling in the A549 human lung cancer cell line." (PMID 33924205, 2021).
ovarian carcinoma (3 papers, 2011 to 2024). A malignant neoplasm originating from the surface ovarian epithelium. "To study Dlx-2 expression in human tumors, we performed real-time PCR using the RNAs extracted from paired biopsy breast, colon, and ovarian cancer tissues and the corresponding normal tissues." (PMID 21917150, 2011). "We also assessed the expression of Dlx-2 protein in human tumors, including breast, colon, and ovarian cancers, with immunohistochemical staining (IHC) in paraffin-embedded and formalin-fixed tissues and compared the results with those of real-time PCR analysis." (PMID 21917150, 2011). "Furthermore, in ovarian cancer, Dlx-2 expression was detected in high-grade tumors that were poorly differentiated but not in the low-grade tumors, which were well differentiated." (PMID 21917150, 2011).
viral infection (3 papers, 2010 to 2020). "In contrast, injection of NeuroD1 plus Dlx2 viruses into the striatum of Cre77.6 transgenic mice revealed a transitional conversion process at different time points following viral infection." (PMID 32107381, 2020). "Characterization of the E12.5 telencephalon from wtShh and ShhN viral infections performed at E9.5 confirms that cortical tissue is ventralized, expressing Dlx2, Dlx5 and Evfc." (PMID 21114856, 2010). "We first confirmed the co-expression of NeuroD1 and Dlx2 with immunostaining after viral infection." (PMID 33425896, 2020).
cleft palate (2 papers, 2022 to 2023). Cleft palate is a fissure type embryopathy that affects the soft and hard palate to varying degrees. "Using this model, we demonstrated that Dlx2 caused cleft palate by affecting maxillary growth and uplift in the early-stage development of maxillary prominences." (PMID 35514355, 2022). "The wnt1cre; Rosa26Dlx2/- mice, with Dlx2 overexpressed in neural crest-derived cells exhibit craniofacial deformities such as cleft palate." (PMID 36891149, 2023). "The wnt1cre; Rosa26Dlx2/- mice that exhibited consistent and synchronized cleft palate phenotype enable us to profile the impact of Dlx2 overexpression on the transcriptome of mouse maxillary processes." (PMID 35514355, 2022).
gastric cancer (2 papers, 2022 to 2025). A primary or metastatic malignant neoplasm involving the stomach. "Notably, gene sets related to digestion, DNA replication, and chromatid segregation were significantly enriched, suggesting that DLX2 may be associated with increased proliferative and metabolic activity in gastric cancer cells." (PMID 41244921, 2025). "To explore whether DLX2 is associated with the immune microenvironment in gastric cancer, we obtained gene expression profiles from various tumors in the TCGA database and classified them into high and low DLX2 expression groups on the basis of the median expression level." (PMID 41244921, 2025). "However, whether the unfavorable outcomes mediated by DLX2 in gastric cancer are linked to EMT remains unknown." (PMID 41244921, 2025). "Our previous analysis identified DLX4 and DLX2 as biomarkers linked to histological grade and prognosis in gastric cancer (GC)." (PMID 41244921, 2025). "The results revealed that after 72 hours of DLX2 overexpression, the number of AGS and HGC-27 cells in the experimental group was significantly greater than that in the control group (pcDNA3.1(+)), indicating a protumorigenic role of DLX2 in gastric cancer." (PMID 41244921, 2025). "Following transient transfection and overexpression of DLX2 in gastric cancer cell lines, Western blot analysis confirmed successful overexpression." (PMID 41244921, 2025). "DLX2 expression was significantly higher in gastric cancer cells than in normal gastric mucosal cells (GES-1)." (PMID 41244921, 2025). "A CCK-8 assay further revealed that DLX2 knockdown suppressed gastric cancer cell proliferation, supporting its oncogenic role in gastric cancer." (PMID 41244921, 2025). "Aberrant DLX2 expression has been reported in a variety of malignancies, including hematologic cancers, breast cancer, and gastric cancer." (PMID 41244921, 2025). "To evaluate the effect of DLX2 on gastric cancer cell migration and invasion, we performed wound healing and Transwell assays." (PMID 41244921, 2025). "Despite these insights, the role of DLX2 in gastric cancer progression—particularly its interaction with EMT and PI3K/AKT signaling—remains largely unexplored." (PMID 41244921, 2025). "The elevated protein expression level of DLX2 in gastric cancer cells is consistent with the RNA sequencing data." (PMID 41244921, 2025). "The results demonstrated that high DLX2 expression significantly reduced the survival rate of gastric cancer patients, with statistically significant differences observed in overall survival (OS), first progression (FP), and postprogression survival (PPS)." (PMID 41244921, 2025). "To assess the functional impact of DLX2 on gastric cancer cells, we performed CCK-8 proliferation assays." (PMID 41244921, 2025). "To further investigate the role of DLX2 in gastric cancer progression, we examined its protein expression levels across various gastric cancer cell lines." (PMID 41244921, 2025). "Next, immune scoring analysis revealed a significant correlation between DLX2 expression and both immune and stromal scores in gastric cancer patients." (PMID 41244921, 2025). "In a study of gastric cancer, increased expression of DLX2 was found to be correlated with more advanced stage, but it was not an independent prognostic factor." (PMID 36317140, 2022). "These in vivo results validate the oncogenic role of DLX2 in gastric cancer." (PMID 41244921, 2025). "To validate the biological function of DLX2 in gastric cancer, we conducted in vivo experiments." (PMID 41244921, 2025). "Similarly, the Transwell assay results revealed that DLX2 overexpression markedly enhanced the migration and invasion of gastric cancer cells." (PMID 41244921, 2025). "Additionally, gene set enrichment analysis (GSEA) based on DLX2 expression levels further revealed enrichment of multiple biological process gene sets in gastric cancer." (PMID 41244921, 2025).